LZTFL1 (leucine zipper transcription factor like 1)
Diseases named in the same sentence as LZTFL1 in open-access papers (continued):
Sharing a sentence is not in itself a finding about the gene and the disease.
tumor (14 papers, 2011 to 2024). "Leucine zipper transcription factor like 1 (LZTFL1) is a gene located on chromosome 3p21.3, which is a tumor suppressor gene (TSG) associated with the signaling pathway that involves E-cadherin (E-cad) and activates EMT." (PMID 36768298, 2023). "The LZTFL1 gene encodes the leucine zipper transcription factor-like 1, and its function is related to tumor-suppressor action and negative regulation of the hedgehog signaling pathways." (PMID 35455670, 2022). "LZTFL1 overexpression significantly suppressed tumor growth in PDX mouse model compared to lentiviruses expressing control vector." (PMID 36966254, 2023). "Leucine Zipper Transcription Factor-like 1 (LZTFL1) is a tumor suppressor located in the chromosome region 3p21.3." (PMID 36966254, 2023). "We instigated the prognostic value of LZTFL1 and compared it with other prognostic factors of ccRCC, including age, Fuhrman grade, tumor necrosis, lymph node invasion, and TNM stage." (PMID 36966254, 2023). "For example, miR-21-5p enhances tumor progression by targeting genes, such as leucine zipper transcription factor like 1 (LZTFL1), programmed cell death 4 (PDCD4), and tropomyosin 1 (TPM1)." (PMID 36768298, 2023). "Analysis of LZTFL1 CNA distribution showed that only a small number of tumor samples (n = 6) have gain of LZTFL1 whereas deep deletion and shallow deletion of LZTFL1 are overrepresented in the TCGA database (n = 57 deep deletion and n = 406 shallow deletion)." (PMID 36966254, 2023). "As a tumor-suppressor gene, leucine zipper transcription factor-like 1 (LZTFL1) regulates metastasis by blocking β-catenin translocation to the nucleus and activating pro-metastatic gene expressions, such as slug and snail." (PMID 33917233, 2021). "The low expression of LZTFL1 was correlated with the tumor grades and metastasis and predicted poor patient outcome." (PMID 31293455, 2019). "Functionally, LZTFL1 serves as a tumor suppressor and a negative regulator in the hedgehog signaling pathways." (PMID 31293455, 2019). "Among the genes common to all four databases, we chose LZTFL1, a key tumor suppressor, as a target for further research because of its vital role in cancer metastasis." (PMID 31351450, 2019). "Previous study found that LZTFL1, acting as a tumor suppressor, was down-regulated in gastric and lung cancer." (PMID 31351450, 2019). "The ectopic expression of LZTFL1 in tumor cells largely reduced the anchorage-independent cell growth and cell migration in vitro and inhibited tumor growth in vivo." (PMID 31293455, 2019). "LZTFL1 re-constitution in tumor cells suppressed the growth of tumor cells derived graft in vivo and inhibited the extravasation/colonization of tumor cells into the lung." (PMID 31293455, 2019). "The re-constitution of LZTFL1 in lung tumor cells suppressed the extravasation/colonization of circulating tumor cells into the lung and inhibited tumor growth in vivo." (PMID 31293455, 2019). "Immunohistochemistry results indicated that LZTFL1 was highly expressed in the epithelial cells of normal tissues and showed significantly lower expression in the corresponding tumor samples including breast, liver, ovary, stomach, lung, and thyroid cancer." (PMID 31293455, 2019). "Clinically, LZTFL1 expression level displayed significant correlation with longer survival time of cancer patients and had significantly inverse correlation with tumor metastasis." (PMID 31293455, 2019). "Finally, we show that overexpression of LZTFL1 in patient-derived xenografts (PDX) inhibited tumor growth." (PMID 36966254, 2023). "The effect of LZTFL1 on tumor cell growth is likely due to its inhibition on AKT." (PMID 36966254, 2023). "In conclusion, we have identified a novel tumor suppressive function of LZTFL1 in ccRCC." (PMID 36966254, 2023). "Since the EMT is a crucial mechanism in tumor metastasis, we next speculated that the miR-21/LZTFL1 axis is involved in the EMT." (PMID 31351450, 2019).
tumor (continued). "Moreover, the protein expression level of LZTFL1 was significantly decreased in tumor tissues with miR-21 overexpression." (PMID 31351450, 2019). "Functionally, LZTFL1 was first confirmed to be a tumor suppressor." (PMID 31293455, 2019). "Recently, tumor suppressor function of LZTFL1 has been proposed." (PMID 22072986, 2011). "The authors reported that LZTFL1 was part of C3CER1 (chromosome 3 common eliminated region 1) at 3p21.3, which is regularly lost during tumor formation." (PMID 37547597, 2023). "Human LZTFL1 is located ∼5 Mb from the LUCA region on the telomeric end of the 3p21.3 region, a hotspot for tumor-suppressor genes." (PMID 31293455, 2019). "Moreover, a previous study showed that ZNRF1 interacts with Leucine Zipper Transcription Factor-like 1 (LZTFL1), which is a tumor suppressor that inhibits the G1 to S phase cell cycle transition by destabilizing AKT." (PMID 39748950, 2024). "Without the inhibitory action of miR-21-5p, the LZTFL1 gene is able to increase the expression of E-cad in tumor cells when it begins to decrease by suppressing the β-catenin nuclear translocation, which oppositely increases miR-21-5p." (PMID 36768298, 2023). "No side effects of lentiviral-delivery of LZTFL1 were observed on tumor-bearing mice." (PMID 36966254, 2023).
cancer (13 papers, 2011 to 2024). A tumor composed of atypical neoplastic, often pleomorphic cells that invade other tissues. "Studies have shown that LZTFL1 is significantly downregulated in several type of cancers, which associated with shorter overall survival of patients." (PMID 31351450, 2019). "Previously, we identified LZTFL1 as a target of miR-106b-5p that promotes RCC aggressiveness and found that lower LZTFL1 expression was associated with shorter overall survival time (OS) of ccRCC patients through analysis of LZTFL1-mRNA in The Cancer Genome Atlas (TCGA) pan-cancer database." (PMID 36966254, 2023). "The study reports a new target gene for miR-21 which is the Leucine zipper transcription factor-like 1 (LZTFL1), a key gene regulating cancer metastasis." (PMID 39684767, 2024). "Another miR-21 target is LZTFL1, which is suppressed in the presence of miR-21 overexpression and contributes to cancer metastasis." (PMID 36726376, 2023). "We established a PDX model with fresh ccRCC tissue and evaluated the effect of LZTFL1-targeted cancer therapy via intra-tumoral injection of lentiviruses expressing LZTFL1 (twice weekly, for a total of 10 times)." (PMID 36966254, 2023). "Among the genes we reported in patients who died, LZTFL1 is known to inhibit epithelial-mesenchymal transition (EMT) in the lungs in the presence of inflammation or cancer." (PMID 36371196, 2022). "Mechanically, LZTFL1 was reported to regulate β-catenin signaling which then activated the EMT in several cancers." (PMID 31351450, 2019). "Leucine zipper transcription factor-like 1 (LZTFL1) is one of the key genes which regulate cancer metastasis." (PMID 31351450, 2019). "For instance, miR-21-5p could enhance the spread of HBC by targeting cancer suppressive genes, such as leucine zipper transcription factor like 1 (LZTFL1), programmed cell death 4 (PDCD4), and tropomyosin 1 (TPM1)." (PMID 34967265, 2022). "Mutations simultaneously occurring in LZTFL1 and CCR9 were the most frequent across cancers." (PMID 35141230, 2021). "Also, zebrafish is a well-established genetic model system for development, immunology, homeostasis, and cancer study, but LZTFL1 study in zebrafish is limited." (PMID 31293455, 2019). "Research indicates that LZTFL1 plays a vital role in regulating the EMT process in several cancers." (PMID 31351450, 2019). "LZTFL1 maps to human chromosome 3p21.3, which is often deleted in several types of cancer." (PMID 22072986, 2011). "The LZTFL1 upregulation sequesters the EMT process and improves the survival rate in some cancers as well as inhibiting the metastatic effect of the EMT30,31." (PMID 38956433, 2024). "LZTFL1 acts as a tumor suppressor gene by regulating the β-catenin signaling pathway, and once lost, it activates the Epithelial-to-Mesenchymal Transition (EMT)-related pathways in several types of cancer." (PMID 39684767, 2024). "The up-regulation of miR-21 in this cancer induces the silencing of several tumor suppressor genes, such as programmed cell death 4 (PDCD4) and leucine zipper transcription factor-like 1 (LZTFL1)." (PMID 34885130, 2021).
infection (7 papers, 2021 to 2023). The state of being infected such as from the introduction of a foreign agent such as serum, vaccine, antigenic substance or organism. "Another recent study reported the existence of at least three independent association signals in the 3p21.31 region, with one at LZTFL1 being more strongly associated with severity of infection, and the other two at SLC6A20 being primarily associated with susceptibility to infection." (PMID 35768520, 2022). "Several variants (rs17763742 near LZTFL1, rs2834164 in IFNAR2 and rs1826292621 near TLE1) showed a significant difference in effect sizes (SNP*sex interaction P < 0.0031, adjusted probability for 16 comparisons) linked not only to hospitalization, but also to critical illness and infection risk." (PMID 35708486, 2022). "Furthermore, in addition to nonsynonymous differences in LZTFL1, CCR9, FYCO1, and SLC6A20A/B, regulatory differences were seen for genes in this locus at baseline as well as in the context of infection." (PMID 35862771, 2022).
LZTFL1 also shares sentences with these, for which no sentence is quoted: ciliopathy (2 papers); Hypertension (2); autoimmune disease (1); Bardet-Biedl syndrome 1 (1); beta thalassemia (1); Cognitive impairment (1); colon cancer (1); cone-rod dystrophy (1); dementia (1); diabetes (1); frontometaphyseal dysplasia (1); hepatocellular carcinoma (1); Meckel syndrome type 13 (1); Meckel syndrome, type 2 (1); osteofibrous dysplasia (1); polydactyly (1); pulmonary fibrosis (1); renal cell carcinoma (1); retinal ciliopathy (1); retinal degeneration (1); Sepsis (1); spondylometaphyseal dysplasia (1); type 2 diabetes (1); Usher syndrome (1); viral pneumonia (1).